KDM4C (lysine demethylase 4C)
Diseases named in the same sentence as KDM4C in open-access papers (continued):
Sharing a sentence is not in itself a finding about the gene and the disease.
gastric cancer (9 papers, 2017 to 2025). A primary or metastatic malignant neoplasm involving the stomach. "Consistently, immunoblotting detected a profoundly elevated protein level of KDM4C in gastric cancer from our cohort." (PMID 37848946, 2023). "In gastric cancer, ALDH1A3 causes 5-fluorouracil and cisplatin resistance in connection with the histone demethylase and oncogene Lysine Demethylase 4C (KDM4C)." (PMID 36672441, 2023). "Collectively, these data suggest that KDM4C might act as a potential biomarker for diagnosing gastric cancer clinical outcomes and further highlights the clinical therapeutic values of QC6352." (PMID 37848946, 2023). "Besides, high KDM4C transcripts levels predicted the poor outcomes in patients with gastric cancer." (PMID 37848946, 2023). "Notably, little is known about the role of KDM4C in gastric cancer." (PMID 37848946, 2023). "Concerning the epigenetic regulation of ALDH1A3 expression, feed-forward regulation between a histone demethylase, KDM4C, and ALDH1A3 has been reported in gastric cancer stem cells." (PMID 38669046, 2024). "In turn, ALDH1A3 increases KDM4C levels, thereby establishing a KDM4C-ALDH1A3 feedforward regulation which results in chemoresistance in gastric cancer." (PMID 36672441, 2023). "Here, we show that the silencing of KDM4B, but not KDM4A/KDM4C, with specific shRNAs significantly reduced IL-8 production in gastric cancer cells." (PMID 30683841, 2019).
osteosarcoma (9 papers, 2011 to 2025). A usually aggressive malignant bone-forming mesenchymal neoplasm, predominantly affecting adolescents and young adults. "Overexpression of KDM4C was found in non-small cell lung carcinoma and osteosarcoma, where upregulation of fibroblast growth factor 2, promoted by KDM4B/C modulates cell migration, invasion, and proliferation in osteosarcoma metastasis." (PMID 34778065, 2021). "Quercetin (WO2007104314) is a natural flavonoid that was found to inhibit KDM4C in demethylation assays and to modify H3K9me3 demethylation status in esophageal carcinoma and bone osteosarcoma cells." (PMID 34778065, 2021).
breast tumors (8 papers, 2012 to 2025). "Overall, our data in clinical samples and experimental models suggest an oncogenic role for KDM4C in a subset of basal breast tumors." (PMID 40457074, 2025).
melanoma (6 papers, 2019 to 2022). A malignant, usually aggressive tumor composed of atypical, neoplastic melanocytes. "Targeting relevant demethylases such as LSD1 or KDM4C had deleterious effects on melanoma growth by inducing senescence." (PMID 35654819, 2022). "In melanoma cells, enforced expression of KDM4C promoted melanomagenesis through altered methylation of relevant target histone residues." (PMID 35654819, 2022).
ovarian carcinoma (6 papers, 2020 to 2025). A malignant neoplasm originating from the surface ovarian epithelium. "Plant-derived molecule luteolin was shown to bind to KDM4C, and in ovarian cancer cells, it significantly decreased proliferation, sphere formation, and expression of markers of cancer stem cells like SOX2, OCT4, and NANOG proteins, and ALDH1 activity." (PMID 40940894, 2025). "Luteolin can be used to treat prostate cancer (JPRN-jRCTs041230029), and inhibit ovarian cancer stem cells proliferation by interfering with the KDM4C/PPP2CA/YAP pathway (ChiCTR2200056567)." (PMID 40620671, 2025). "In the current study, we found that KDM4C, a histone demethylase, was required for ovarian cancer stem cell (CSC) maintenance." (PMID 32908544, 2020). "Altogether, these results indicated that KDM4C is required for maintenance of CSC characteristics in ovarian cancer cells." (PMID 32908544, 2020). "In this study, we used the sphere culture approach to enrich the CSC population of ovarian cancer and found that KDM4C is upregulated in the tumospheres." (PMID 32908544, 2020). "We screened 21 histone demethylases and identified that KDM4C is upregulated in both SK-OV-3 and HO-8910 cells, suggesting a role of KDM4C in regulating “stemness” of ovarian cancer cells." (PMID 32908544, 2020). "Depletion of KDM4C reduced the sphere-forming, colony-forming ability and the proportion of ALDHhigh population in ovarian cancer cells." (PMID 32908544, 2020). "Additionally, KDM4C is involved in maintaining the stem cell properties of cancer cells in ovarian cancer and AML." (PMID 38623585, 2024). "Furthermore, we evaluated the aldehyde dehydrogenase (ALDH) activity, a known stem cell feature, of ovarian cancer cells after KDM4C knockdown using flow cytometry." (PMID 32908544, 2020). "In summary, we identify a crucial role of KDM4C in the maintenance of CSCs in ovarian cancer." (PMID 32908544, 2020). "We observed a similar elevation of KDM4C mRNA expression and a significant decrease of KDM3C expression when comparing the adherent and sphere culture of HO-8910 ovarian cancer cells." (PMID 32908544, 2020). "Furthermore, the knockdown of KDM4C sensitized hepatoma cancer cells to cisplatin, and the knockdown of KDM4A effectively sensitized resistant ovarian cancer cells to cisplatin." (PMID 40940894, 2025). "Furthermore, we found that depletion of KDM4C inhibits the migration, invasion, and CSC properties of ovarian cancer cells." (PMID 32908544, 2020).
squamous cell carcinoma (6 papers, 2016 to 2023). A carcinoma arising from squamous epithelial cells. "Using in vitro cell line models, KDM4C has been implicated in different cancers including squamous cell carcinoma, B-cell lymphoma, and prostate, and breast cancers." (PMID 26766589, 2016). "In particular, GASC1 (gene amplified in squamous cell carcinoma, also known as KDM4C, a histone demethylase) promotes chromosomal instability and transcription initiation, therefore, plays a causative role in cancer cells driven by its dysregulation." (PMID 37863956, 2023). "More KDM genes, including KDM4B, KDM2B, and KDM4A for adenocarcinomas and KDM2B, KDM4C, and KDM4B for squamous cell carcinomas, appear to be associated with patients’ survival." (PMID 29619118, 2018). "Caffeic acid is an inhibitor of the histone demethylase KDM4C/JMJD2C, also known as gene amplified in squamous cell carcinoma 1 (GASC1)." (PMID 35968782, 2022).
glioblastoma (5 papers, 2021 to 2026). The most malignant astrocytic tumor (WHO grade IV). "Although epigenetic dysregulation by KDM4C has emerged as an important mechanism in several cancers, the molecular mechanisms underlying the contribution of KDM4C to cell proliferation and tumorigenesis remain to be further elucidated in glioblastoma." (PMID 33462212, 2021). "Overexpression or genomic amplification of KDM4C has been reported in multiple cancers, including prostate, breast, lung, and glioblastoma, correlating with enhanced cellular proliferation, invasion, and metastatic capacity." (PMID 41505486, 2026). "In glioblastoma cells, KDM4C binds to the promoter region of c-Myc to increase the demethylation of histone 3 (H3) at Lys9 (H3K9me3), promoting c-Myc expression and tumorigenesis." (PMID 38786726, 2024). "A correlation was reported between the overexpression of histone demethylases (KDM4C) and c-Myc transcripts in human glioblastoma tissue." (PMID 38786726, 2024). "For example, KDM4C can induce the transcription of Wnt/β-catenin target genes and promote glioblastoma tumorigenesis." (PMID 37117173, 2023). "To gain molecular insights into the mechanism by which KDM4C regulates glioblastoma growth and viability, we investigated the expression of key cell cycle and apoptotic regulatory proteins using immunoblot assays." (PMID 33462212, 2021). "Our study demonstrates KDM4C inhibition as a promising therapeutic strategy for targeting glioblastoma." (PMID 33462212, 2021). "Among the 29 KDMs, KDM4C expression was the only one significantly higher in glioblastoma tissues compared to control ones." (PMID 33462212, 2021). "In parallel, an analysis of GEO profiles (GSE36245) in 35 patients with glioblastoma revealed a positive correlation between the expression of KDM4C and c-Myc." (PMID 33462212, 2021). "To address the importance of KDM4C in glioblastoma cell growth and viability, we downregulated KDM4C in U87 and U251 glioblastoma cells using siRNAs or shRNA." (PMID 33462212, 2021). "However, KDM4C’s roles in glioblastoma and the underlying molecular mechanisms remain unclear." (PMID 33462212, 2021). "Altogether, our results suggest that KDM4C epigenetically promotes the expression of the oncogene c-Myc by directly binding to its promoter and erasing H3K9me3 marks in glioblastoma cells." (PMID 33462212, 2021). "Our findings demonstrate that the histone demethylase KDM4C is essential for the tumor progression of glioblastoma." (PMID 33462212, 2021). "The growth curve revealed that knockdown of KDM4C in glioblastoma cells resulted in significant short-term and long-term growth inhibition compared to that in the control groups of the two cell lines." (PMID 33462212, 2021).
glioblastoma (continued). "KDM4C protein expression is upregulated in glioblastoma, and its expression correlates with c-Myc expression." (PMID 33462212, 2021). "Here, we show that KDM4C knockdown significantly represses proliferation and tumorigenesis of glioblastoma cells in vitro and in vivo that are rescued by overexpressing wild-type KDM4C but not a catalytic dead mutant." (PMID 33462212, 2021). "We examined whether KDM4C depletion affects the expression of its target genes in glioblastoma cells." (PMID 33462212, 2021). "In the present, we investigated the function of KDM4C in glioblastoma development and progression." (PMID 33462212, 2021). "Our results demonstrated that KDM4C was highly expressed in glioblastoma cells and tissues." (PMID 33462212, 2021). "Based on the overexpression of KDM4C in glioblastoma, we speculated that KDM4C might regulate the proliferation of glioblastoma cells." (PMID 33462212, 2021). "In addition, knockdown of KDM4C induced the apoptosis of glioblastoma cells, as demonstrated by the increase in annexin V/PI-positive cells and upregulation of cleaved caspase-3 and cleaved poly(ADP ribose) polymerase (PARP)." (PMID 33462212, 2021). "To investigate whether KDM4C is involved in the tumorigenesis of glioblastoma, we used a doxycycline-inducible (Tet-On) KDM4C shRNA system in U87 cells." (PMID 33462212, 2021). "KDM4C positively correlated with c-Myc expression in human glioblastoma cell lines and tissues." (PMID 33462212, 2021). "In contrast, KDM4C overexpression induced the expression of c-Myc in glioblastoma cells." (PMID 33462212, 2021). "We conclude that KDM4C depletion promotes apoptosis in glioblastoma cells." (PMID 33462212, 2021). "Moreover, the expression and function of KDM4C and its mechanisms of action in glioblastoma are largely unknown." (PMID 33462212, 2021). "Immunoblot analysis revealed that KDM4C and KDM4D protein levels were highly expressed in most of the glioblastoma cell lines, whereas the protein levels of KDM4A and KDM4B were very low or not detected." (PMID 33462212, 2021). "Another KDM4C target gene, MDM2, exhibited a similar expression correlation pattern in glioblastoma samples." (PMID 33462212, 2021). "KDM4C is a histone H3K9 demethylase that contributes to epigenetic regulation of both oncogene and tumor suppressor genes and is often overexpressed in human tumors, including glioblastoma." (PMID 33462212, 2021). "Although the role of KDM4C in glioblastoma is not well investigated, KDM4C has been reported to be an oncogene in other cancers." (PMID 33462212, 2021). "Furthermore, the inhibitory effect of shKDM4C on the cell growth and viability was rescued by wt KDM4C but not by demethylase dead mutant KDM4C H190A, suggesting that the activity of KDM4C is essential for glioblastoma cell proliferation and survival." (PMID 33462212, 2021). "Therefore, targeting KDM4C as an indirect Myc-targeting approach may be a promising novel cancer therapy for glioblastoma." (PMID 33462212, 2021). "KDM4C and c-Myc expressions were positively correlated, whereas those of KDM4A, KDM4B, and KDM4D did not correlate with c-Myc in glioblastoma." (PMID 33462212, 2021).
hepatocellular carcinoma (5 papers, 2021 to 2026). A malignant tumor that arises from hepatocytes. "Overexpression of KDM4C has been implicated in various malignancies, including breast, prostate, colorectal, and hepatocellular carcinomas, hence it is promising drug target." (PMID 41505486, 2026). "Our study highlights the therapeutic potential of natural polyphenolic compounds as inhibitors of KDM4C, an oncogenic epigenetic regulator implicated in cancers like breast, prostate, colorectal, and hepatocellular carcinoma." (PMID 41505486, 2026). "KDM4C silencing enhanced RT sensitivity in hepatocellular cancer cells in vitro, which was associated with impairment of homologous repair (HR) pathway." (PMID 40940894, 2025). "Next, we measured the protein level of KDM4C in human HL-7702 normal liver cells and several hepatocellular carcinoma cell lines." (PMID 37117173, 2023). "Moreover, KDM4C silencing reduced IR radiation-induced Rad51-foci formation, pointing to impaired HR repair of DSB in hepatocellular cancer cells." (PMID 40940894, 2025).
esophageal cancer (4 papers, 2013 to 2024). A primary or metastatic malignant neoplasm involving the esophagus. "Contemporarily, esophageal cancer patients are being considered for clinical research for testing caffeic acid, which is capable of inhibiting KDM4C’s demethylation activity." (PMID 37218871, 2023). "The most important KDM4 inhibitor is caffeic acid, a naturally occurring substance found in several sources, including Eucalyptus globulus, which has been discovered to primarily target KDM4C and has strong anti-cancer efficacy against esophageal cancer, both in vitro and in vivo." (PMID 37218871, 2023). "Thus far, only one of the KDMs, KDM4C/GASC1, has been found to be modified in esophageal cancer cell lines and might be involved in cancer development." (PMID 24146981, 2013). "GASC1, a family number of KDM4 and also named KDM4C, was identified and cloned from the 9p24-amplified region of esophageal cancer cell lines." (PMID 32411232, 2020).
autism spectrum disorder (3 papers, 2014 to 2020). A spectrum of developmental disorders that includes autism, and Asperger syndrome. "Also, there might be a common locus for OCD and autism spectrum disorders at rs301443 residing between SLC1A1 and JMJD2C (Lysine-specific demethylase 4C/KDM4C) at 9p24." (PMID 25017045, 2014).
myeloproliferative neoplasm (3 papers, 2022 to 2025). A clonal hematopoietic stem cell disorder, characterized by proliferation in the bone marrow of one or more of the myeloid (i.e., granulocytic, erythroid, megakaryocytic, and mast cell) lineages. "The histone demethylases KDM4C (JMJD2C) and KDM3C (JMJD1C) were recently identified as signaling effectors of mutated JAK2 and target genes of the transcription factor NFE2, which is overexpressed in myeloproliferative neoplasms." (PMID 40140631, 2025). "Given the fact that KDM4C was dispensable for normal hematopoietic stem- and progenitor cells, targeting this enzyme may represent a strategy to selectively target JAK2-mutated cells in myeloproliferative neoplasms." (PMID 35654819, 2022).